LAMC1 (laminin subunit gamma 1)
Diseases named in the same sentence as LAMC1 in open-access papers (continued):
Sharing a sentence is not in itself a finding about the gene and the disease.
prion disease (2 papers, 2020 to 2023). A transmissible disease that is caused by a protein that is able to induce abnormal folding of normal cellular proteins, leading to characteristic spongiform brain changes, which are associated with neuronal loss without an inflammatory response. "LAMC1 was involved in different inflammation and immune response pathways, including prion diseases (bovine spongiform encephalopathy), amoebiasis and toxoplasmosis in cattle." (PMID 37600659, 2023).
rectal cancer (2 papers, 2025). A primary or metastatic malignant neoplasm that affects the rectum. "We highlight subsite-specific effects, such as rectal cancer risk linked to LAMC1, a clinically actionable drug target, and identify CCM2 expression as a female-specific CRC risk factor involved in progesterone signalling." (PMID 40447568, 2025). "We found genetically predicted increased expression of LAMC1 was associated with increased rectal cancer risk, providing support for therapeutic inhibition of LAMC1." (PMID 40447568, 2025). "We also identify a female-specific association with CRC risk for CCM2 expression and subsite-specific associations, including LAMC1 with rectal cancer risk." (PMID 40447568, 2025).
adenomyosis (1 paper, 2021). The growth of endometrial tissue inside the muscular wall of the uterine corpus. "The expression levels of ITGA1, ITGB1, LAMC1, and CKM are downregulated in the adenomyosis group compared with those in control group, while those proteins are successfully recovered by anti-NGF treatment." (PMID 32676925, 2021). "Western blotting confirmed that the expression levels of integrin alpha-1 (ITGA1), integrin beta-1 (ITGB1), laminin subunit gamma-1 (LAMC1), and creatine kinase M-type (CKM) were decreased in adenomyosis group, whereas those levels were elevated after anti-NGF treatment." (PMID 32676925, 2021). "In the present study, the expression level of LAMC1 was not different between adenomyosis group and control group." (PMID 32676925, 2021). "It was also prompt that LAMC1 might not play a vital role in impaired endometrial receptivity in mice with adenomyosis." (PMID 32676925, 2021). "Furthermore, ITGB1, ITGA1, LAMC1, and CKM might participate in the recovery of adenomyosis." (PMID 32676925, 2021).
atherosclerosis (1 paper, 2022). A disease characterized by the build-up of fatty material and calcium deposition in the arterial wall resulting in partial or complete occlusion of the arterial lumen. "New association signals from cross-ancestry GWASs included, for example, variants at PROCR, GRK5 and F11 (thrombosis), LPA and ATP2B1 (lipid metabolism, hypertension and atherosclerosis), SWAP70 (membrane ruffling) and LAMC1 (cerebrovascular matrisome)." (PMID 36180795, 2022).
bladder cancer (1 paper, 2022). "Consistent to our results in vitro, a poor overall survival of bladder cancer patients with high LAMC1 (encoding laminin submit gamma 1) expression was observed by utilizing TCGA database analysis." (PMID 35585515, 2022).
cardiomyopathy (1 paper, 2020). A disease of the heart muscle or myocardium proper. "Laminin Subunit Gamma 1 (LAMC1) is a member of the ECM-receptor interactions and Focal adhesion pathways that have been associated functionally with cardiomyopathy previously (cf. “Discussion” section)." (PMID 33060801, 2020).
cervical carcinoma (1 paper, 2022). A carcinoma arising from either the exocervical squamous epithelium or the endocervical glandular epithelium. "LAMC1 expression is studied in the tissue of some types of cancers including, hepatocellular or cervical carcinomas." (PMID 35373932, 2022).
chronic myeloid leukemia (1 paper, 2024). "Among these genes, MTOR, STAT3, MCL1, LAMC1, and KRAS have been reported to play roles in imatinib resistance in chronic myeloid leukemia in parallel with our findings." (PMID 38916832, 2024).
colon adenocarcinoma (1 paper, 2024). "Additionally, a negative correlation between the expression levels of miR-423-5p and LAMC1 was observed in patients with colon adenocarcinomas." (PMID 39684686, 2024).
diabetic retinopathy (1 paper, 2025). "Diabetic retinopathy (DR), a leading cause of adult blindness, with LAMC1-mediated epithelial-mesenchymal transition (EMT) playing a key role." (PMID 41092639, 2025).
ependymoma (1 paper, 2023). A WHO grade II, slow growing tumor of children and young adults, usually located intraventricularly. "By evaluating gene expression of the PFA ependymoma tumors in our cohort, we found that LAMC1 transcription is increased in the 1q+ PFA ependymoma relapse tumors as compared to primary PFA ependymoma tumors." (PMID 37085539, 2023).
epilepsy (1 paper, 2022). A brain disorder characterized by episodes of abnormally increased neuronal discharge resulting in transient episodes of sensory or motor neurological dysfunction, or psychic dysfunction. "Structurally, the laminin subunit α5 forms heterotrimers with laminin subunits β1/β2 and γ1/γ3, which were encoded by LAMB1, LAMB2, LAMC1, and LAMC3 that were associated with neurodevelopmental diseases and epilepsy." (PMID 35663266, 2022).
esophageal cancer (1 paper, 2025). A primary or metastatic malignant neoplasm involving the esophagus. "Overexpression of LAMC1 is involved in the progression of gynecologic cancers and predicts poor prognosis in gastric and esophageal cancers." (PMID 41458559, 2025).
fibrosis (1 paper, 2018). the formation of excess fibrous connective tissue in an organ or tissue in a reparative or reactive process. "The developed LG1M assay detects a degradation fragment of LAMC1 which is released by MMP-9, an MMP known to be highly upregulated in fibrosis." (PMID 30273365, 2018).
Huntington disease (1 paper, 2022). Huntington disease (HD) is a rare neurodegenerative disorder of the central nervous system characterized by unwanted choreatic movements, behavioral and psychiatric disturbances and dementia. "At the same time, gene sets related to oxidative phosphorylation, Huntington’s disease, and Parkinson’s disease were differentially associated with the low LAMC1 expression phenotype." (PMID 36188228, 2022).
hypertriglyceridemia (1 paper, 2025). A laboratory test result indicating elevated triglyceride concentration in the blood. "Genes mapping to approved or investigational drugs included CALCRL (target of several medications used to manage migraine disorder), LAMC1 (target of ocriplasmin, used to treat vitreomacular traction), and ANGPTL4 (investigational target for hypertriglyceridemia)." (PMID 40874306, 2025).
Infertility (1 paper, 2025). "Also, menstrual blood serum was characterized as a less invasive source of infertility biomarkers, where EMILIN1, TRIP6, LAMB1, LAMC1, NID1, APOB, APOA4 were detected as the main differences in uIF patients as compared to healthy controls." (PMID 40861859, 2025).
Intellectual disability (1 paper, 2022). "The LAMC1 gene has been repeatedly reported in Dandy–Walker malformation with occipital cephalocele, and most of the affected individuals had an infant-onset intellectual disability with or without seizures." (PMID 35663266, 2022).
kidney cancer (1 paper, 2022). Primary or metastatic malignant neoplasm involving the kidney. "Of the three members of the LAMC family, LAMC1 and LAMC2 were upregulated in kidney cancers, while LAMC3 was downregulated in kidney cancers." (PMID 36188228, 2022).
muscle atrophy (1 paper, 2020). The loss of muscle tissue due to inactivity or disease. "In summary, we identified miR‐29b‐3p as a muscle atrophy‐associated exosomal miRNA with potential to be uptake by neuronal cells which consequently inhibits neuronal cell differentiation via targeting the mRNAs of c‐FOS, BCL‐2, RIT1, LAMC1, and upregulation of lncRNA HIF1α‐AS2." (PMID 32233025, 2020).
psoriasis (1 paper, 2024). An autoimmune condition characterized by red, well-delineated plaques with silvery scales that are usually on the extensor surfaces and scalp. "Communication between hair follicle cells and Langerhan cells was associated with COL4A2/CD44 and LAMC1/CD44 in psoriasis, contrasting with a relatively weak HBEGF/EGFR ligand-receptor pair in normal skin." (PMID 38289616, 2024).
renal carcinoma (1 paper, 2022). A carcinoma arising from the epithelium of the renal parenchyma or the renal pelvis. "These opposite prognostic features of LAMC1 overexpression in the two types of renal carcinoma may be related to different tumor immune microenvironments and immunomodulator-associated molecules." (PMID 36188228, 2022).
SAPHO syndrome (1 paper, 2019). SAPHO syndrome (acronym for Synovitis, Acne, Pustulosis, Hyperostosis and Osteitis) is an auto-inflammatory disease, mainly characterized by the association of neutrophilic cutaneous involvement and chronic osteomyelitis. "Components of laminin (LAMA4, LAMB1 and LAMC1) and MCAM also help cell adhesion and slow-rolling of neutrophils, the up-regulation of whom indicated excessive neutrophil activation and migration in SAPHO syndrome." (PMID 31395074, 2019).
small cell lung carcinoma (1 paper, 2023). Small cell lung cancer (SCLC) is a highly aggressive malignant neoplasm, accounting for 10-15% of lung cancer cases, characterized byrapid growth, and early metastasis. "Downstream target proteins including LAMC1, LAMC3, CDK2 and FN1 were enriched in the cancer‐related pathways in small cell lung cancer." (PMID 35668574, 2023).
Stroke (1 paper, 2014). Sudden impairment of blood flow to a part of the brain due to occlusion or rupture of an artery to the brain. "New genes to be considered for vascular restoration after stroke included Col6a3, Fn1, and Lamc1." (PMID 24672479, 2014).
tauopathy (1 paper, 2025). Neurodegenerative disorders involving deposition of abnormal tau protein isoforms (tau proteins) in neurons and glial cells in the brain. "APOE ε4 amplifies tau pathology via hub genes: In P301S tauopathy mice, female APOE ε4 boosted expression of Lrp10, Ltbp2, Lamc1, and Rbms2, revealing a potential link to the acceleration of tau-driven neurodegeneration." (PMID 41409615, 2025).
virus infection (1 paper, 2021). "We checked whether a direct correlation could be established between susceptibility to virus infection and LAMC1 gene expression levels." (PMID 34158478, 2021).
cancer (49 papers, 2014 to 2025). A tumor composed of atypical neoplastic, often pleomorphic cells that invade other tissues. "LAMC1 expression was associated with DSS of various cancers, including BLCA, LGG, MESO, and UVM (P < 0.001)." (PMID 38678297, 2024). "LAMC1 encodes laminin γ1, which is involved in a variety of processes such as normal tissue development, cancer cell invasion and metastasis." (PMID 35511773, 2022). "Then, we performed univariate Cox regression for all the ECM genes in the meta-cohort and identified LAMC1, which encodes laminin subunit gamma 1, an essential component of the basement membrane that is involved in multiple types of cancer progression, as the risk factor with the lowest p-value." (PMID 34646782, 2021). "We highlight CLPTM1L, LAMC1, and BABAM1 here due to previously-reported pleiotropic associations across multiple cancers." (PMID 40775447, 2025). "Although some biological functions of LAMC1 have been reported, the research on LAMC1 based on pan cancers and the mechanism of regulating LAMC1 expression are still unclear." (PMID 38678297, 2024). "We comprehensively analyzed the expression and prognostic value of the LAMC1 gene across pan-cancers." (PMID 38678297, 2024). "Cox proportional risk model analysis showed that LAMC1 expression levels were significantly correlated to OS of patients with KIRP, LGG, MESO, and UVM (P < 0.001) and many other cancer types (P < 0.05)." (PMID 38678297, 2024). "The top enriched pathways for the upregulated genes included focal adhesion, regulation of actin cytoskeleton and pathway in cancer, as well as the key upregulated genes included LAMC1, MYL9, COL1A, and KAT2A which, regulate ECM formation and actin skeleton." (PMID 39735192, 2024). "We also found statistical significance between LAMC1 expression and the partial tumor stage in eight cancer types, including BLCA, COAD, HNSC, KICH, KIRC, LUSC, PAAD, and UVM." (PMID 38678297, 2024). "To further evaluate association of LAMC1 and immune microenvironment in RCC, we analyzed the relation of LAMC1 expression to the Cancer-Immunity Cycle, immune neoantigens appearance and tumor mutational burden (TMB)." (PMID 36188228, 2022). "The number of cancer cells was much higher than fibroblasts in tumor environment, so tumor cells were considered as the primary source of LAMC1." (PMID 35541892, 2022). "Our results showed that most of activities of Cancer-Immunity Cycle were higher in high LAMC1 expression groups in KIRC and only just a few steps showed higher immunoactivity in KIRP." (PMID 36188228, 2022). "Many of the ECM components that showed differential expression and were highlighted in the hypernetwork analysis, including MMPs, TIMP3, FN1, LAMC1, and COL4A1/6A2, have previously been reported as prognostic or diagnostic markers in different cancers." (PMID 35267606, 2022). "We also evaluated the role of LAMC1 in the activity of cancer-related pathways and drug sensitivity in RCC by GSCALite." (PMID 36188228, 2022). "Subunit gamma-1 (LAMC1) was downregulated in all four cancer types, while all other subunits showed lower expression levels in SCLC; LAMC2, LAMA5, LAMB2 in LCC; and LAMA5, LAMB2, LAMA3 in AC as well." (PMID 35681609, 2022). "We also provide evidence of a direct correlation between LAMC1 expression levels and H-1PV oncolytic activity in 59 cancer cell lines and in 3D organotypic spheroid cultures with different sensitivities to H-1PV infection." (PMID 34158478, 2021). "Accordingly, at the protein level, LAMC1 was more highly expressed in cancer tissues than in para‐cancer tissues, as demonstrated by IHC staining and was also associated with low OS and tumor stage." (PMID 34218518, 2021). "Laminin interactions, including that of LAMC1, have been shown to promote oncogenesis via processes including cancer cell migration, differentiation and metastasis." (PMID 32660466, 2020).
cancer (continued). "Despite the tumorigenic role of LAMC1 in different cancers, its potential regulatory mechanism needs to be investigated." (PMID 31884422, 2019). "LAMC1 is targeted by agents like Ocriplasmin and Lanoteplase, mainly used for non-cancer conditions, but may be repurposed due to its role in the tumor microenvironment." (PMID 40496862, 2025). "Versican (VCAN) and LAMC1, which are strongly associated with tumor progression and increased metastasis risk, were identified only in CRLM-SD, whereas TIMP3 and decorin, which are linked to an opposing effect in cancer, were found exclusively in CRLM-CA." (PMID 40617497, 2025). "LAMC1 belongs to the laminin family of extracellular matrix proteins that are significantly involved in survival and proliferation of cancer cells, angiogenesis, migration and basement membrane breach by cancer cells, and metastatic events." (PMID 40775447, 2025). "By integrating transcriptomic and proteomic data in multitrait colocalization, 13 pleiotropic loci influenced CAD and cancer risk via differential gene or protein expression of neighboring genes, including CALCRL, ANGPTL4, and LAMC1, targets of approved or investigational medications." (PMID 40874306, 2025). "Therefore, with the development of technology and the improvement in clinical diagnosis and treatment methods, LAMC1 is expected to provide new treatment strategies for malignant tumor patients." (PMID 38678297, 2024). "Knowledge of the biological features and clinical relevance of LAMC1 in cancers remains limited." (PMID 38678297, 2024). "However, in SN, cancer cells interact with other cells through a complex formed by collagen family genes, LAMC1, and integrin subunits." (PMID 37745301, 2023). "The results showed that the LAMC1 levels in LAMC1-knockout cancer cells CM were also decreased." (PMID 35541892, 2022). "In line with these early reports, it appears that high expression of LAMC1 may be involved in the progression of kidney disease, including cancer." (PMID 36188228, 2022). "LAMC1 is reportedly involved in the progression of various malignant tumors." (PMID 34268116, 2021). "Interestingly, elevated levels of LAMA4 and LAMC1 are observed in cancer cells, which suggests that their upregulation in SIRT1-depleted adipocytes reflects their hyperplastic phenotype." (PMID 33854178, 2021). "For example, LAMC1 in the “focal adhesion” pathway has been implicated in processes such as cell adhesion, differentiation, migration, signaling, neurite outgrowth, and metastasis; miR-29a/b regulates this pathway and inhibits cancer cell migration and invasion by targeting LAMC1." (PMID 25705681, 2015). "LAMC1 may participate in signaling pathways involved in formation of adherens junction and basement membrane in KIRP and KIRC, and the high expression of LAMC1 is resistant to most drugs or small molecules of the Genomics of Drug Sensitivity in Cancer database." (PMID 36188228, 2022). "These included multitrait colocalization at 6 loci with a consistent direction of effect between CAD and cancer (ABO, PGAP3, ANGPTL4, SREBF1, HAUS6, and SYNJ2BP) and 7 with an opposing direction (CDKN1A, RGS19, CALCRL, SF3A3, LAMC1, MYO9B, and MIA3)." (PMID 40874306, 2025). "Patients that showed higher LAMC1 expression in KIRP were 20–40 years old, female, of advanced nodal metastasis status and advanced stages of cancer (stage 3–4)." (PMID 36188228, 2022). "Patients that showed higher LAMC1 expression in KIRC were 20–40 years old and in the early stages of cancer (stage 1–2)." (PMID 36188228, 2022). "We consequently explored the expression of LAMC1 in different clinicopathological parameters of KIRP and KIRC, including age, gender, nodal metastasis status, and cancer stage, based on the UALCAN database." (PMID 36188228, 2022). "This study uncovers that PSMA3-AS1 functions as a cancer-promoting gene in CCA, and PAX5/PSMA3-AS1/miR-376a-3p/LAMC1 axis plays a vital role in CCA development." (PMID 35022330, 2022).
cancer (continued). "Among the predicted mRNA targets of miR-22 are known cancer-related genes such as phosphatase and tensin homolog (PTEN), metadherin (MTDH), cyclin-dependent kinase 6 (CDK6), and laminin γ1 (LAMC1)." (PMID 24748979, 2014). "LAMC1 binds to integrin (ITGA3-ITGB1) receptors, inducing the activation of the laminin signaling pathway, further leading to the formation of extracellular matrix, hindering the recruitment of immune effector cells into the TME to exert anti-cancer effects." (PMID 40589640, 2025). "In addition, this panel includes ECM components that stimulate cancer cell invasion, such as collagens (e.g., COL1A1, COL4A1), the extracellular matrix glycoproteins laminins (e.g., LAMA1, LAMC1), fibronectin (FN1), and SPARC, among others." (PMID 38437557, 2024). "Although an early report mentioned a relationship between LAMC1 and hypoxia, our current study clarified the regulatory relationship between HIF-1α and LAMC1 expression, which expands our understanding of the molecular mechanism of ECM remodeling in the hypoxic microenvironment of malignant tumors." (PMID 38678297, 2024). "However, LAMC1 hypomethylation in KIRP and KIRC weakly correlates with prognosis in cancer patients." (PMID 36188228, 2022). "Those pathways specifically altered in primary tumors were associated with an abnormally increased expression of genes that are involved in focal adhesion (e.g., PRKCA, CRK, and BCL2), PI3K-Akt signaling (e.g., PHLPP2, PRKCA, PPP2R3A and KIT) and cancer pathways (e.g., COL4A5, LAMC1 and BCL2L1)." (PMID 27662660, 2016).